MMP9 (matrix metallopeptidase 9)
Diseases named in the same sentence as MMP9 in open-access papers (continued):
Sharing a sentence is not in itself a finding about the gene and the disease.
tumor (continued). "Among MMPs, the overexpression of MMP-2 and MMP-9 and their increased activities are closely related to BM and ECM decomposition, which increased tumor cell invasion and migration ability." (PMID 40149594, 2025). "In LUAD, especially metastatic tumor cells, the increased expression of MMP-2 and MMP-9 levels is related to basement membrane (BM) and extracellular matrix (ECM) degradation." (PMID 40149594, 2025). "The epithelial-mesenchymal transition (EMT) cascade constitutes a pivotal mechanism in tumor metastasis, with E-cadherin, N-cadherin, VEGF, and MMP-9 representing essential molecular markers involved in this biological process." (PMID 41472816, 2025). "In contrast, N2 neutrophils suppress T cell activity, display a reduced cytotoxicity against tumor cells, and secrete high levels of pro-tumoral factors, like VEGF, IL-8, and MMP-9, thus promoting angiogenesis, tumor growth, and metastasis." (PMID 40136347, 2025). "Both PGPs and PGPs-NE markedly improved these parameters, with PGPs-NE showing greater effectiveness in reducing tumor weight, restoring antioxidant levels, and inhibiting the expression of PCNA, MMP-9, and IL-6." (PMID 41307829, 2025). "A crucial mechanism by which EGFRvIII enhances OSCC invasion is through upregulation of matrix metalloproteinases (MMPs), particularly MMP2 and MMP9, which degrade ECM components to facilitate tumor dissemination." (PMID 40472740, 2025). "Neutrophils play a crucial role in tumor angiogenesis by releasing pro-angiogenic factors such as VEGF and MMP-9." (PMID 40486614, 2025). "In this sense, the substantial increase in COL1A1 and other ECM remodelling-related genes, such as MMP9 and TNC, after IL-36γ stimulation in HT- 29 cells underscores the role of this cytokine in modulating the tumour microenvironment." (PMID 40268791, 2025). "When isorhamnetin interacts with the cancer cell, it downregulates key molecular markers playing a key role in tumor progression, including MMP-2 and MMP-9 (matrix metalloproteinases accountable for degrading the basement membrane)." (PMID 40806510, 2025). "Direct cleavage: Nanoparticles composed of MMP-9-cleavable materials, such as gelatin, are degraded in MMP-9-rich environments such as tumor microenvironments and vasculopathies, facilitating local drug release." (PMID 40284474, 2025). "The observed effects of cannabinoids on AGS cells were also studied on gastric xenografts, decreasing the tumor volume by 30% and decreasing invasion (MMP2/MMP9/MMP8)." (PMID 40076652, 2025). "IF1 expression levels were positively related to those of VE-cadherin, vimentin, MMP2, and MMP9, while they were negatively related to E-cadherin, indicating that IF1 can promote tumor progression by enhancing the EMT and VM formation." (PMID 41306771, 2025). "It is known that matrix metalloproteinases (MMPs), including MMP7, MMP9, and MMP12, are secreted by both tumor and stromal cells, and they function to regulate metastasis by degrading extracellular matrix." (PMID 40750784, 2025). "This aligns with evidence that high APOC1 expression enhances the secretion of cytokines, such as EGF, PDGF, VEGFA, IL-1, IL-8, TNF-α, MMP-9, MMP-2, and NO, which collectively drive tumor cell proliferation, invasion, and angiogenesis." (PMID 39873475, 2025). "In addition, MMP-2 and MMP-9 promote tumor progression by modulating the tumor microenvironment through the activation of chemokines and proinflammatory cytokines, which recruit immune cells that may support tumor growth and survival." (PMID 40563423, 2025). "Its activation suppresses MMP2 and MMP9, which are involved in ECM degradation and tumor cell invasion." (PMID 40564023, 2025). "In turn, mTOR activation has been shown to upregulate MMP-2 and MMP-9—downstream effectors that degrade the ECM and facilitate tumour cell invasion." (PMID 40860666, 2025).
tumor (continued). "One such enzyme, matrix metalloproteinase 9 (MMP-9), facilitates extracellular matrix remodeling and promotes angiogenesis to support tumor growth." (PMID 39941753, 2025). "In turn, TANs release proteases, such as MMP-9 and lipocalin-2 (LCN2) to degrade the extracellular matrix (ECM) and disrupt the BBB, thereby enabling tumor cell extravasation." (PMID 41219968, 2025). "L. plantarum YYC-3 has demonstrated remarkable efficacy in suppressing CRC cell growth, invasion and migration, significantly reducing the expression of key genes like MMP2, MMP9 and VEGFA that are crucial for tumor angiogenesis and metastasis." (PMID 40520902, 2025). "MMP-9 (matrix metalloproteinase-9) and MMP-14 (matrix metalloproteinase-14) drive tumor invasion and growth by degrading extracellular matrix (ECM) proteins." (PMID 39975023, 2025). "Tumor-associated macrophages (TAMs), particularly of the M2 phenotype, secrete matrix metalloproteinases (MMPs) such as MMP-9 and MMP-2, which degrade collagen and other ECM components, thereby facilitating tumor cell migration and metastasis." (PMID 40787464, 2025). "MMP-9 also releases ECM-bound growth factors (VEGF, TGF-β), enhancing tumor vascularization and immune evasion." (PMID 41303402, 2025). "Previous studies have identified COX-2 as a key mediator of tumor metastasis, primarily through its stimulation of inflammatory mediators that upregulate MMP2 and MMP9 expression, thereby enhancing the metastatic potential of cancer cells." (PMID 41009473, 2025). "The expression of lncRNA RP11-297P16.4 was negatively correlated to the level of miR-145-5p in NSCLC cells, which sponged miR-145-5p and suppressed tumor cell migration and invasion by targeting matrix metalloproteinase 2 (MMP-2) and MMP-9." (PMID 40149594, 2025). "TAMs also secrete VEGF and MMPs, such as MMP-9 and MMP-11, which are crucial for tumor dissemination." (PMID 40399946, 2025). "NE promotes invasion by directly degrading ECM proteins and activating protease cascades 119, while MMP-9 disrupts ECM integrity by degrading type IV collagen in the basement membrane, facilitating tumor cell dissemination." (PMID 40365275, 2025). "Due to NF-κB stimulation in tumor cells, MMP-2 and MMP-9 break down ECM type IV collagen during cancer invasion and metastasis." (PMID 40563423, 2025). "It reduces the expression of chemokines MCP-1 and RANTES, which are essential for TAM recruitment, and further suppresses TAM activation by decreasing M2 macrophage markers and tumor-promoting factors like MMP-2, MMP-9, and VEGF." (PMID 40330466, 2025). "MMP-9 plays a role in releasing VEGF bound to the extracellular matrix, facilitating their interaction and promoting angiogenesis in the tumor-adjacent tissues, including the lumbar artery perforator region." (PMID 40026939, 2025). "Concurrently, Matrix Metalloproteinase 9 (MMP9), a zinc-dependent endopeptidase, is critically involved in the degradation of the extracellular matrix (ECM), a process fundamental to tumor invasion and metastatic dissemination." (PMID 41302727, 2025). "Co-expression with known tumor markers (e.g., KLK3, MMP9) reinforces DOCK3’s tumor-specific expression signature." (PMID 41200217, 2025). "In contrast, N2 phenotype neutrophils promote tumor proliferation and metastasis by secreting a range of substances such as vascular endothelial growth factor (VEGF) and matrix metallopeptidase 9 (MMP-9), which stimulate tumor angiogenesis." (PMID 41445740, 2025). "Classical tumour markers, including MMP2, MMP9, PCNA, and Ki67, had significantly decreased mRNA expression in the siRNA group." (PMID 41284374, 2025). "MMP-9 can degrade the extracellular matrix (ECM) components and has an important role in tumor invasion and metastasis." (PMID 39881131, 2025). "While members of the transgelin family can suppress metastasis through ERK1/2 modulation and MMP-9 downregulation, TAGLN2 has shown both tumor-suppressive and oncogenic roles depending on the cancer type." (PMID 41148856, 2025).
tumor (continued). "Elevated MMP9 activity in HCC drives the proteolytic cleavage of MHC class I chain-related protein A (MICA), leading to the release of soluble MICA and enabling tumor immune evasion." (PMID 40283942, 2025). "MMP-9 and CD44, both involved in tumor invasion and metastasis, have demonstrated varying degrees of utility." (PMID 40422614, 2025). "Hypoxia-induced EVs from PCa cells have been shown to carry active MMP2 and MMP9, which remodel the ECM at pre-metastatic niches, preparing distant bone environments for tumour seeding." (PMID 40806577, 2025). "To assess the impact of PMAIP1 knockdown on tumor proliferation and metastasis, we utilized the proliferation marker Ki67 and the metastasis markers MMP2 and MMP9 for further analysis." (PMID 39944827, 2025). "After FOXCUT and FOXC1 (an EMT-related gene) silencing, the expression levels of MMP2, MMP7, MMP9, and VEGF-A were downregulated, suggesting a possible role for the FOXC1/FOXCUT gene pair in tumor angiogenesis in OSCC." (PMID 41020820, 2025). "Conversely, inhibition of MMP-9 suppresses EMT, thereby slowing tumor progression, prolonging survival." (PMID 41463322, 2025). "Increased P2X7R expression was found to significantly correlate with the expression levels of 5 ‘tumour-promoting’ mediators – VEGFB, IL-4, MMP-9, PCNA and IL-8." (PMID 41034696, 2025). "Molecular analyses supported these findings, showing significant downregulation of tumor-promoting genes, including VEGF, MMP-9, and IL-6, as well as upregulation of the anti-inflammatory cytokine IL-10." (PMID 40808199, 2025). "QRHXF also decreased MMP2 and MMP9 protein expression levels, mitigating ECM degradation in NSCLC and suppressing tumor migration and invasion." (PMID 40670983, 2025). "Through suppression of the HMGB1/TLR4 axis, AS-IV reduced M2 macrophage-mediated production of pro-tumor factors such as TGF-β, matrix metalloproteinase 9 (MMP-9), and IL-10." (PMID 40417220, 2025). "In the tumor, matrix metalloproteinase-9 (MMP-9), once activated, can degrade and destroy type IV collagen and ECM gelatin near the tumor cell surface." (PMID 40266038, 2025). "Neutrophils promote angiogenesis and extracellular matrix degradation by secreting factors such as interleukin-8 (IL-8) and matrix metalloproteinase-9 (MMP-9), accelerating tumor invasion and metastasis." (PMID 41211449, 2025). "They reshape the tumor microenvironment by releasing enzymes like matrix metalloproteinase 9 (MMP-9) and signaling molecules such as vascular endothelial growth factor (VEGF), thereby accelerating tumor progression and metastasis." (PMID 40381082, 2025). "Abnormal expression of metalloproteinases is regulated by HIF-1α, which induces the expression of MMP2, MMP9, ADAM10, etc., in tumor cells, hydrolyzing MICA and MICB on the surface of tumor cells and mediating immune escape." (PMID 40563539, 2025). "The persistent production of pro-inflammatory cytokines (IL-1β, IL-6, TNF-α) and MMPs (especially MMP-9) alters the extracellular matrix, promotes EMT, and supports tumor invasion and metastasis." (PMID 41322070, 2025). "Immunohistochemistry further confirmed decreased expression of p-GSK-3β, MMP-9, and MMP-13 in tumor tissues from ArcA-treated mice." (PMID 39948552, 2025). "EVs are used by tumor cells as carriers for RNA, DNA, receptors, and proteins, including MMP2, MMP9, high mobility group box 1 (HMGB1), and CD147." (PMID 40345526, 2025). "Specifically, we propose that SP influences MMP-9 and MMP-2 activity, thereby facilitating ECM remodeling, tumor invasion, and metastasis." (PMID 40321254, 2025). "By releasing proangiogenic factors, including MMP9 and VEGF‐A, B cells facilitate tumour angiogenesis and support tumour invasion and metastasis." (PMID 40268524, 2025). "Neutrophil proliferation in the TME accelerates tumor angiogenesis, epithelial-mesenchymal transition (EMT), and growth by producing MMP9, NETs, and hepatocyte growth factor, worsening hepatocellular carcinoma and its metastasis." (PMID 40387965, 2025).
tumor (continued). "In the hypoxic bone marrow, MMP9 is involved not only in ECM breakdown but also in osteoclast activation, supporting osteolytic activity and tumour growth." (PMID 40806577, 2025). "Platelet-derived extracellular vesicles (PEVs) are also implicated in this process, as they enhance the expression of MMP-9, VEGF, HGF, and IL-8 in tumor cells, further highlighting the importance of platelets in regulating angiogenesis in the tumor context." (PMID 39934930, 2025). "The polarized neutrophils release MMP9 and S100A8/A9, which degrade the pulmonary basement membrane and promote tumor cell colonization." (PMID 40564894, 2025). "Alternatively, neutrophil-derived MMP9, as well as S100A8 and S100A9, influences tumor cell survival at the metastasizing site." (PMID 39653768, 2025). "This interaction led to the polarization of macrophages into the tumor-promoting M2 phenotype, characterized by increased secretion of IL-10, VEGF, and MMP-9, alongside reduced levels of IL-12 and NO." (PMID 40330466, 2025). "In this context, we detected a significant increase in NGAL, COL1 A1, MMP9, SPP1, TNC and VEGF expression after IL-36 stimulation in HT-29 cells, indicating its potential role in promoting tumour progression through enhanced matrix remodelling." (PMID 40268791, 2025). "Further, collagenase (MMP8) and gelatinase B (MMP9), which facilitate the invasion of tumor cells are also secreted by N2-TAN." (PMID 40230883, 2025). "MMP-9, being an extracellular matrix (ECM) degrading enzyme plays a predominant role in promoting tumor angiogenesis, invasion and metastasis." (PMID 41181711, 2025). "MMPs like MMP-9 are particularly important in breaking down collagen and other ECM components, allowing tumor cells to invade surrounding tissues." (PMID 40486614, 2025). "Endothelial cells recruit TEMs to tumour sites by upregulating Ang-2, and TEMs exert their angiogenic activity by secreting a series of angiogenic factors, such as VEGF, MMP9, COX2 and Wnt5A." (PMID 39847394, 2025). "Among these, matrix metalloproteinase (MMP) family members—including MMP1, MMP3, MMP9, and MMP11—exhibited significant upregulation, consistent with their established roles in promoting tumor invasiveness." (PMID 40361356, 2025). "MMP9 is a zinc-dependent proteolytic enzyme that degrades extracellular matrix (ECM) collagen, which can facilitate tumor invasion and metastasis." (PMID 40839565, 2025). "Kupffer cells (liver-resident macrophages) and recruited immune cells secrete MMP9 and MMP14, enabling matrix remodeling and facilitating tumor cell invasion or colonization." (PMID 41463352, 2025). "Although it usually acts as a tumor suppressor by inhibiting migration and invasion by regulating MMP2 and MMP9, its overexpression in metastatic cases indicates either a compensatory mechanism or context-specific functionality." (PMID 39958058, 2025). "Overproduction of MMP2 or MMP9 leads to the breakdown of critical ECM and BM components, allowing tumor cells to escape and spread further." (PMID 40735254, 2025). "In contrast, N2 TANs are generally pro-tumor and can promote tumor growth through elastase secretion while releasing MMP8, MMP9, and VEGF to facilitate metastasis and angiogenesis." (PMID 40724900, 2025). "Matrix metalloproteinases (MMPs), particularly MMP-2 and MMP-9, are crucial enzymes that degrade the ECM, significantly contributing to the remodeling of the extracellular environment and promoting tumor progression." (PMID 40670983, 2025). "Motile tumour cells frequently overexpress MMPs, such as MMP-8 and MMP-9, which cleave chemokines like CXCL9 and CXCL10, disrupting chemotactic gradients and diminishing T-cell infiltration." (PMID 40361472, 2025). "Recent studies indicated that when co-cultured with GC cells, M2-polarized TAMs secreted matrix metalloproteinase 9 (MMP9) as a result of COX-2 upregulation, thereby facilitating tumor angiogenesis." (PMID 40599798, 2025).
tumor (continued). "Metastatic tumor cells also secrete IL‐23, which induces TNF‐α production in LSECs, upregulating MMP9 and ICAM1 expression and promoting the formation of endothelial cell gaps." (PMID 40027151, 2025). "Elevated CCL5 expression in prostate cancer enhances tumor cell migration and invasion, upregulating N-cadherin, MMP2, MMP9, and the CD44+CD133+ cell subpopulation." (PMID 39286635, 2024). "N2 TANs also secrete collagenase (MMP8) and gelatinase B (MMP9), which facilitate the invasion of tumour cells by remodelling the extracellular matrix." (PMID 38218739, 2024). "Glabridin inhibits tumor cell migration and invasion by suppressing the NF-κB, AP-1, and JNK1/2 pathways, downregulating MMP-9." (PMID 39723390, 2024). "The combination therapy of TACE and RLX can significantly increase the expression of MMP-9 and MMP-2 in tumor tissue (p < 0.001)." (PMID 38955827, 2024). "N2-type TANs can produce MMP-9, remodel the ECM, and release growth factors such as VEGF to promote tumor angiogenesis." (PMID 39691707, 2024). "RNH1 knockdown upregulated the expression of PCNA and MMP9, and RNH1 overexpression declined it, suggesting that RNH1 inhibited LUAD tumor formation in vivo." (PMID 38783241, 2024). "In this study, immunohistochemistry was used to detect the expressions of EMT-related protein MMP9 and Snail in the PKHD1(-/+) and the normal control tumor-bearing mice." (PMID 39512694, 2024). "Consistently, Ki67, MMP2, MMP9, c-Myc, β-catenin, CDK4, CDK6, and Cyclin D1 protein levels in tumor tissues were significantly decreased by SAMD5 overexpression but partially increased by PLK1 overexpression." (PMID 39524172, 2024). "Previous studies have reported that MMP2, MMP9 and TWIST are important functional proteins involved in VM formation in tumor cells." (PMID 39050762, 2024). "Modified GZT inhibited GC tumor growth and reduced metastasis and invasion-related proteins expression levels, including CD147, VEGF, and MMP-9." (PMID 38195483, 2024). "The expression of MMP-9 was very low in the saline group, indicating the weak invasive ability of SCC7 tumor cells." (PMID 39027362, 2024). "Regulation of tumor angiogenesis by PD-L1 has been previously confirmed alongside its correlation with VEGF expression and MMP-9 inhibition, with erianin showing downregulation of both VEGF and MMP-9 expression via PD-L1 silencing." (PMID 39690423, 2024). "Immunohistochemical analysis showed decreased MMP9 and CD31 levels, suggesting reduced tumor invasion and angiogenesis." (PMID 39381427, 2024). "Immunohistochemical staining of tumor tissues showed that the expression levels of HIF-1α, VEGF, and MMP-9 decreased, which improved the hypoxic tumor microenvironment and inhibited tumor metastasis." (PMID 38951911, 2024). "We employed scRNA-seq analyses to investigate the communication between MICA+ tumor cells and MMP9+ macrophages via the PROS1-AXL axis and revealed an upregulation of the IFN-γ signaling pathway in MICA+ tumor cells." (PMID 38254761, 2024). "Next, we investigated the mRNA expression of MMP1, MMP9 and FMOD in tumor cells after they were cocultured with different CAFs in 2D." (PMID 38822309, 2024). "The most significant findings included the transcriptional upregulation of MMP1 (125-fold), ADAM28, MMP9, and ADAM9 (5.2-fold, 4.4-fold, and 4.2-fold upregulated) in tumor tissue compared to normal skin." (PMID 38891088, 2024). "In contrast to claudin-1, meta-analysis suggests that MMP-1, MMP-2, MMP-9, and VEGF are highly expressed in RB, which are highly correlated with poor cell tumor differentiation, tumor invasion, and clinically advanced stage." (PMID 38920989, 2024). "Matrix metalloproteinase 2 (MMP2) and 9 (MMP9), cathepsin, CCL18, and CYP4A promote extracellular matrix (ECM) breakdown and stimulate tumour dissemination." (PMID 38920685, 2024).